TNF (tumor necrosis factor)
Diseases named in the same sentence as TNF in open-access papers (continued):
Sharing a sentence is not in itself a finding about the gene and the disease.
lung adenocarcinoma (continued). "We detected the mRNA quantity of TIM-3, TNF-α, and IFN-γ in 40 surgically resected specimens from patients with lung adenocarcinoma by real-time quantitative polymerase chain reaction (qRT-PCR)." (PMID 36865498, 2023). "To further analyze the relationship between the high expression of Tim-3 and lymph node metastasis, we detected the expression of TNF-α and IFN-γ proteins in normal tissues, paracancerous tissues, and tumor tissues in patients with lung adenocarcinoma." (PMID 36865498, 2023). "Experiments in the latest oncology research regarding PRKCDBP as a transcriptional target of TNF‐α demonstrated that low expression of PRKCDBP forebode poor prognosis in tumour patients, including those with lung adenocarcinoma." (PMID 36696967, 2023). "In this study, we investigated TIM-3 protein expression and its correlation with TNF-α and IFN-γ by examining the tissues of patients with lung adenocarcinoma." (PMID 36865498, 2023). "Our study showed that the high expression of Tim-3, low expression of TNF-α and IFN-γ, and the synergistic effect of TNF-α and IFN-γ in patients with lung adenocarcinoma were closely related to poor clinicopathological characteristics." (PMID 36865498, 2023). "Subsequently, we detected the mRNA expression of Tim-3, TNF-α, and IFN-γ in normal, paracancerous, and tumor tissues of patients with lung adenocarcinoma and analyzed the correlation between the expression of Tim-3 and TNF-α and IFN-γ in lung adenocarcinoma." (PMID 36865498, 2023). "The high expression of TIM-3, the low expression of TNF-α and IFN-γ, and the synergistic effect of TNF-α and IFN-γ in patients with lung adenocarcinoma were closely related to poor clinicopathological characteristics." (PMID 36865498, 2023). "The genes that increased with fivefold following co‐culture with all lung adenocarcinoma cell lines were CD80 (B7‐1), IL‐7, IL‐15, and TNF." (PMID 34907653, 2022). "The present results demonstrated that cucurbitacin B down-regulated TNF-α-induced ICAM-1 expression and the NF-κB signaling pathway in human lung adenocarcinoma A549 cells." (PMID 35806134, 2022). "By mining existing sequencing data, we further demonstrate that the expression levels of TNF and TACE are significantly decreased in lung adenocarcinoma patients, while the TNFR1/TNFR2 balance are increased." (PMID 34445397, 2021). "TNF, WNT10A, PDGFA, and NRG1 derived from infiltrated dendritic cells in lung adenocarcinoma microenvironment were proved to worsen neuropathic pain associated with cancers by sensitizing sensory neurons." (PMID 32434423, 2020). "We have previously reported that TNF-α, an inflammatory cytokine, enhances TGF-β-induced EMT in A549 lung adenocarcinoma cells." (PMID 32357159, 2020). "Therefore, the purpose of this study was to investigate whether PRFR exerts anticancer effects through suppression of the TNF-α-induced expression of the survival and metastasis proteins by inhibiting the MAPKs, NF-κB, and AP-1 signaling pathways in A549 human lung adenocarcinoma cells." (PMID 31540489, 2019). "In this study, we found increased TNF-α and IL-6 expression and macrophages infiltration in AFG1-induced lung adenocarcinoma." (PMID 28801561, 2017). "We treated A549 with AFG1 and/or TNF-α with IL-6 to investigate to the key contributor of EMT and migration in AFG1-induced lung adenocarcinoma." (PMID 28801561, 2017). "Immunohistochemically, higher level of TNF-α and IL-6 expressions in cancer cell were observed in AFG1-induced lung adenocarcinoma." (PMID 28801561, 2017). "qRT/PCR and Western blot results showed that the expression of TNF-α and IL-6 at the mRNA and protein levels were significantly upregulated in AFG1-induced lung adenocarcinoma tissues." (PMID 28801561, 2017). "In A549 lung adenocarcinoma cells, TGF-β elicited EMT in Smad-dependent manner and TNF-α accelerated this process, as confirmed by cell morphology, expression of EMT markers, capacity of gelatin lysis and cell invasion." (PMID 23437179, 2013).
lung adenocarcinoma (continued). "We further analyzed the correlation between the two inflammatory factors, and our data showed that the protein and mRNA of the two inflammatory factors were positively correlated, indicating that the expressions of TNF-α and IFN-γ in lung adenocarcinoma were synergistic." (PMID 36865498, 2023). "In a previous study from our laboratory EMT was induced in A549 lung adenocarcinoma cells, ACHN kidney adenocarcinoma cells derived from metastatic pleural sites, and MCF10A immortalized breast cells using a combination of TGF-β and TNF-α, and gene expression was analyzed using microarray protocols." (PMID 34681055, 2021). "Meanwhile, according to the results of qRT-PCR, it is speculated that ginseng can treat lung adenocarcinoma by up-regulated JUN, IL-1β, IL-2, ICAM1, HMOX1, MMP9, and MMP2 targets and down-regulated PTGS2 and TNF genes." (PMID 32802118, 2020). "All above results suggest that SOD-2 upregulation upon inflammation responses may contribute to TNF-α-mediated EMT and migration in tumor cells in AFG1-induced lung adenocarcinoma." (PMID 28801561, 2017). "Taken together, the results suggest that TNF-α working together with IL-6 could promote EMT and migration in A549 cells, and TNF-α is the key contributor of EMT and migration in AFG1-induced lung adenocarcinoma." (PMID 28801561, 2017). "The expression of TNF-α, IL-6, and macrophage marker CD68, as well as E-cadherin, vimentin, Twist, matrix metalloproteinase (MMP)-2, MMP-9, and SOD-2 were examined in AFG1-induced lung adenocarcinoma." (PMID 28801561, 2017). "However, the addition of blocking antibodies against both TNFα and TNF receptor (TNFR) significantly inhibited the lysis of antibody-coated A549 lung adenocarcinoma cells." (PMID 27670158, 2016). "Our data suggest that the expression of Tim-3 mRNA in lung adenocarcinoma tissues is higher than that in paracancerous tissues and normal tissues, but when the expression of Tim-3, TNF-α, and IFN-γ mRNA is analyzed separately with lymph node metastasis, the results show no statistical significance." (PMID 36865498, 2023). "The co-culture system of primary lymphatic endothelial cells and lung adenocarcinoma cells found that TNF-α significantly increased the concentration of CCL21 in lymphatic endothelial cell culture medium and could promote the invasion and metastasis of lung adenocarcinoma cells." (PMID 33158173, 2020). "Pro-inflammatory signals, such as tumor necrosis factor-α (TNF-α), lipopolysaccharide (LPS), or interferon-γ (IFN-γ), promote the expression of UT, while UII induces the secretion of cytokines, such as interleukine-6 (IL-6), in UT transfected human cardiomyocytes and lung adenocarcinoma cells." (PMID 28487672, 2017). "In our hands, a proteasome inhibition regimen designed to target NF-κB activation of lung adenocarcinoma limited MPE formation by suppressing the expression of multiple paracrine mediators of intrapleural adenocarcinoma dissemination and fluid extravasation, including TNF and CCL2." (PMID 20219102, 2010). "Human lung adenocarcinoma A549 cells were preincubated with ACA for 1 h, and were then incubated with or without TNF-α for 6 h." (PMID 40142019, 2025).
Thrombocytopenia (88 papers, 2008 to 2026). A reduction in the number of circulating thrombocytes. "Severe thrombocytopenia is closely linked to hemophagocytic activity or the suppression of bone marrow hematopoiesis induced by inflammatory cytokines such as TNF-α and IFN-γ." (PMID 41158863, 2025). "Anti-TNF-α agents carry the risk of severe side effects, including thrombocytopenia, which should be monitored closely in the first few months of therapy." (PMID 40958800, 2025). "TNF‐enhanced (tumor necrosis factor) endothelial cell permeability, the depletion of fibrinogen, and lower levels of factors V and II are the causes of thrombocytopenia seen in Marburg hemorrhagic fever (MHF)." (PMID 37662539, 2023). "Our data also demonstrate that thrombocytopenia is associated with an increase in IL-1, IL-6, IL-8, IL-10, and TNF-α." (PMID 34585667, 2021). "Meanwhile, the pSS-associated thrombocytopenia group displayed a trend toward increasing levels of TNFα expression." (PMID 33767707, 2021). "These association indicate that IL-1β and TNF-α probably induces liver tissue injury, vascular damage and thrombocytopenia." (PMID 33436908, 2021). "IL-6, IL-10 and TNF production has been associated with thrombocytopenia in P. vivax malaria patients." (PMID 30199554, 2018). "A subset of cytokines consisting of IL-1β, IL-8, IL-6, TNF-α, and IL-10 was also coordinately high and significantly associated with severity of thrombocytopenia in HA patients." (PMID 28628633, 2017). "MCP-1, along with TNF-α, has been associated with thrombocytopenia; in our mouse model we observed a significant decrease in the platelet count at day 10 p.i, which is proceeded by increased production of both TNF-α and MCP-1 on days 6 and 8 (respectively)." (PMID 21695193, 2011). "Antitumor necrosis factor-α (TNF-α) drugs can be an effective treatment for rheumatoid arthritis and other autoimmune conditions, though they do carry the risk of rare but serious side effects such as thrombocytopenia." (PMID 40958800, 2025). "The immune dysregulation in ITP not only causes thrombocytopenia but also triggers a persistent low-grade systemic inflammatory response through the activation of pro-inflammatory cytokine networks, such as interleukin-6 (IL-6) and tumor necrosis factor-α (TNF-α)." (PMID 41211279, 2025). "This case adds to present literature regarding antitumor necrosis factor-alpha (TNF-α)-induced thrombocytopenia and explores the use of thrombopoietin receptor agonist medications in refractory drug-induced immune thrombocytopenia (DITP)." (PMID 40958800, 2025). "Previous studies have shown that the virus does not directly cause endothelial damage; instead, cytokines such as Tumor necrosis factor-alpha (TNF-α), and interleukins (IL-1β, and IL-6) contribute to thrombocytopenia and immune hyperactivation." (PMID 40573398, 2025). "SFTSV infection triggers a cytokine storm (e.g., elevated IL-6, IL-10, TNF-α), resulting in direct vascular endothelial damage and increased permeability, which contribute to thrombocytopenia and multiorgan dysfunction." (PMID 40794812, 2025). "Our findings reveal significantly elevated sCP levels in SFTS patients, positively correlated with viral load, thrombocytopenia severity, and multiple pro-inflammatory cytokines (TNF-α, IL-6, IL-8, IL-10)." (PMID 40657502, 2025). "A high IL-10 to TNF-α ratio, observed in the control group of both studies, and severe thrombocytopenia observed in the control group of Study 1, indicative of acute leptospiral disease, were detected." (PMID 40732660, 2025). "The treatment also significantly reduced disease severity factors such as vascular leakage, thrombocytopenia; mRNA transcript levels of proinflammatory cytokines such as IL-1β and TNF-α; and restored liver function." (PMID 40189910, 2025).
Thrombocytopenia (continued). "Both the conditions result in the hype of inflammatory cytokines including interleukin-6 (IL-6) and tumor necrosis factor-α (TNF-α) thrombocytopenia, vascular microthrombosis and multi-organ dysfunction." (PMID 39678231, 2024). "Our observation that patients with homozygous TNF-α (A/A) or TNF-β (G/G) genotypes or combined genetic polymorphisms had significantly lower platelet counts suggests that these genetic polymorphisms could be implicated in the severity of thrombocytopenia and might affect disease severity." (PMID 36802017, 2023). "Platelet transfusion to reduce thrombocytopenia, was found to decrease the plasma levels of various inflammatory cytokines such as IL-6 and TNF‐α, and thus improving survival." (PMID 36451834, 2022). "The TNF-α and procalcitonin were elevated to higher levels in the thrombocytopenia group, with the difference attaining significance at 1–10 days compared to the non-thrombocytopenia group." (PMID 35791362, 2022). "In particular, in clinical trials and post-marketing reports, pancytopenia, leukopenia, neutropenia, aplastic anemia, and thrombocytopenia were identified in patients who received monoclonal antibodies including TNF blockers." (PMID 34660652, 2021). "As expected, increased levels of the pro-inflammatory cytokine TNFα associated with both severity of AKI (plasma creatinine elevation) and thrombocytopenia." (PMID 33690725, 2021). "For haematologic toxicities, it was noticed that grade 3/4 thrombocytopenia in the TNF + N group was significantly higher than that in the TPF + P group (15.9% vs. 6.2%, P = 0.020)." (PMID 33123269, 2020). "Using a mouse model, we discovered that TAA-induced acute liver damage is associated with the induction of thrombocytopenia and increased plasma anti-PLT Ig, and TNF-α levels." (PMID 31767905, 2019). "In comparison with NT groups, the TNF-α levels were found to be gradually increased with increasing intensity of thrombocytopenia during Pv, Pf, and mixed infections (p<0.05)." (PMID 31110658, 2019). "In this study, the samples were analyzed for the prevalence and assessment of degree of thrombocytopenia, as well as for cytokines such as TNF-α, IL-6, and IL-10." (PMID 31110658, 2019). "Hypotension, leukopenia, thrombocytopenia, fever, headache, nausea and hepatopathy represent the most common side effects detected in Phase II studies with recombinant TNF, while most serious toxicities include respiratory failure and coagulopathies." (PMID 31803362, 2019). "Elevated TNF-α levels induce thrombocytopenia resulting in platelet trapping and consumption that occurs in inflamed blood vessels." (PMID 31110658, 2019). "In our study the TNF-α levels were found to be significantly increased with increasing severity of thrombocytopenia across all infecting species." (PMID 31110658, 2019). "We have also observed some aspects of human disease, such as thrombocytopenia, liver damage, and increases of IFNγ and TNFα cytokine production when this animal model was infected with a laboratory adapted DENV-1 (Mochizuki strain)." (PMID 26415508, 2015). "For instance, elevated levels of HBP and CRP in conjunction with increased TNF-α and IL-6 can serve as early indicators of severe disease, while thrombocytopenia may signal impending complications such as DIC." (PMID 40963970, 2025). "Additionally, EIII-SNPs induce exacerbated thrombocytopenia, worsen hemorrhage pathogenesis, and the induction of pro-inflammatory cytokines TNF-α, IL-1β, IL-6, and anti-inflammatory cytokine IL-10 in mice." (PMID 37298220, 2023). "We summarized the existing literature on thrombocytopenia induced by anti-TNF-α drugs." (PMID 36386149, 2022). "Additionally, in patients with higher a-SOFA scores, the impairment in TNFα production correlated with thrombocytopenia over the course of disease." (PMID 33690725, 2021). "However, 15.9% of patients in the TNF + N group had grade 3/4 thrombocytopenia in comparison with 6.2% in the TPF + P group (P = 0.020)." (PMID 33123269, 2020).
Thrombocytopenia (continued). "TNF-α was differentially regulated in wild-type versus BCD mice during TAA treatment, and anti-TNF treatment drastically ameliorated antiplatelet Ig induction, thrombocytopenia, and liver injury, suggesting that the TNF pathway plays a critical role in the disease progression." (PMID 31767905, 2019). "The thrombocytopenia with decreased RBCs and WBCs could also be related to increased TNF-α production or suppression of the bone marrow by the parasite and its products." (PMID 30843407, 2019). "However, thrombocytopenia, hemoconcentration and systemic TNF-α levels were similar to infected WT mice." (PMID 21206747, 2010). "TNF-α was inversely related to thrombocytopenia with OR = 0.978 (CI, 0.962–0.995)." (PMID 18578883, 2008). "Current hypotheses of antibody-dependent enhancement, virus virulence, and IFN-gamma/TNF α-mediated immuno-pathogenesis are insufficient to explain clinical manifestations of DHF/DSS such as thrombocytopenia and hemoconcentration." (PMID 19117515, 2008). "IL-1β, IL-8, TNF-α and MCP-1 were associated with marked thrombocytopenia." (PMID 18578883, 2008). "YF induces severe coagulopathy mediated by the overexpression of pro-inflammatory cytokines such as TNF-α and IFN-α, whose concentrations correlate with endothelial damage severity, thrombocytopenia, and disseminated intravascular coagulation." (PMID 40585555, 2025). "We identified significant correlations between serum IL-2, IL-6, TNF-α, and VEGF-D levels and thrombocytopenia in DENV-infected patients in the present study, consistent with the findings of other reports." (PMID 35631079, 2022). "IL-2, TNF-α, VEGF-D, and IL-6 were correlated with thrombocytopenia and these markers were valuable for predicting bleeding." (PMID 35631079, 2022). "Elevated levels of inflammation markers, including interleukin 6 (IL-6), tumor necrosis factor α (TNF-α), C-reactive protein (CRP) and procalcitonin, were observed at 1–10 days or 11–20 days after symptom onset in the patients with thrombocytopenia." (PMID 35791362, 2022). "We found eight proteins (ITGA2B, ITGB3, VWF, PLEK, TNF, TLR2, BCL2 and BCL2L1) were the core targets of DMAG for the treatment of thrombocytopenia." (PMID 34837956, 2021). "The risk of thrombocytopenia and subsequent major bleeding events should not be ignored in AS patients receiving anti-TNF-α therapy, and close monitoring of platelet counts may be recommended for those AS patients with lower platelet counts before anti-TNF-α therapy." (PMID 33343345, 2020). "The TNF + N group had a similar survival outcome and much less grade 3/4 vomiting compared to the TPF + P group, while the incidence of grade 3/4 thrombocytopenia was higher in the TNF + N group." (PMID 33123269, 2020). "Anti-TNF treatment markedly ameliorated the TAA-mediated induction of anti-PLT Ig, circulating AST and ALT levels, and thrombocytopenia in mice." (PMID 31767905, 2019). "Thus, elevated TNF-α levels may imply a similar role in patients with severe thrombocytopenia." (PMID 31110658, 2019). "A retrospective analysis of clinical data from 290 SFTS patients from the First and Second Affiliated Hospitals of Anhui Medical University confirmed previously reported abnormalities including lymphocytopenia, thrombocytopenia, elevated levels of AST, ALT, LDH, and cytokines (IL‐6, IL‐1β, TNF‐α)." (PMID 41090515, 2026). "eGFR - estimated glomerular infiltration rate; iMCD - idiopathic multicentric Castleman disease; JAK - Janus kinase; TAFRO - the thrombocytopenia, anasarca, fever, reticulin fibrosis, renal insufficiency, and organomegaly clinical subtype; TNF-α - tumor necrosis factor-alpha." (PMID 39944226, 2025). "Lack of TNFR1 or the use of the TNF inhibitor etanercept reduced thrombocytopenia, cytokine expression, lung injury and improved survival of MHV-infected mice." (PMID 36451834, 2022).